ASH1L (ASH1 like histone lysine methyltransferase)
Diseases named in the same sentence as ASH1L in open-access papers (continued):
Sharing a sentence is not in itself a finding about the gene and the disease.
cancer (continued). "ASH1L has been found to be frequently altered in various cancers." (PMID 35061901, 2022). "We found that ASH1L exhibited significantly lower expression in cancer (P = 8.2E−10)." (PMID 35061901, 2022). "Here, we reported an underappreciated partner of ASH1L, transcriptional factor HIF-1α, which directly interacts and co-opts with ASH1L in regulating pro-metastatic genes in invading cancer cells." (PMID 40394007, 2025). "We generated cancer-relevant R2587C, L2624F and D2629H mutants of ASH1LPHD and found that binding of these mutants, especially of R2587C, to H3K4me3 peptide was diminished, suggesting that the impaired function of ASH1LPHD could be potentially linked to aberrant activity of ASH1L." (PMID 40044670, 2025). "ASH1L is an H3K4 and H3K36 HMT amplified in many cancers including breast, uterine, pancreatic, liver, and thyroid cancer and AML." (PMID 39765675, 2024). "However, only the AC1 cluster expressed a high level of HIF-1α transcriptome, and this feature was remarkably reduced in ASH1L-depleted tumors, strengthening the crucial role of ASH1L in regulating HIF-1α transcriptome in invading cancer cells." (PMID 40394007, 2025). "ASH1L rewires histone methylations and cooperates with HIF-1α to induce pro-metastatic transcriptome in invading cancer cells, resulting in monocyte differentiation into lipid-associated macrophage (LA-TAM) and enhancing their pro-tumoral phenotype in the metastatic bone niche." (PMID 40394007, 2025). "Compared to wildtype ASH1L-F3, overexpression of F2260A mutant failed to induce cancer cell migration and invasion, suggesting methyltransferase activity of ASH1L is required for its pro-metastatic role." (PMID 40394007, 2025). "Inhibition of ASH1L has been proposed as a potential therapeutic approach, and small molecule inhibitors of ASH1LSET have already shown promising results in blocking proliferation of cancer cells." (PMID 40044670, 2025). "Given that ASH1L promotes bone metastasis and induces HIF-1α transcriptome, we hypothesize that, in addition to reprogramming pro-metastatic genes in invading cancer cells, ASH1L has a cell-extrinsic role of remodeling the bone niche." (PMID 40394007, 2025). "As M2‐like pro‐tumorigenic TAMs are known to promote cancer cell proliferation and inhibit CD8+ T cell activation, we continued to examine whether ASH1L‐polarized macrophages change their functional properties." (PMID 39377228, 2024).
tumor (10 papers, 2015 to 2025). "and found that loss of ASH1L had a moderate effect on cell proliferation or tumor growth, but it dramatically reduced the migration of PC-3M cells." (PMID 40394007, 2025). "To determine if TAMs are essential to promote metastatic tumor outgrowth in bone driven by ASH1L, we performed macrophage depletion assays in vivo." (PMID 40394007, 2025). "IVIS imaging and ex vivo fluorescence imaging revealed that ASH1L depletion significantly suppressed tumor outgrowth in bone, but this effect was abolished by PX-478 treatment." (PMID 40394007, 2025). "Together with our findings in metastasis xenograft models, these results in the syngeneic model establish ASH1L as an essential epigenetic determinant in metastatic tumor outgrowth in the bone." (PMID 40394007, 2025). "AS‐99, a small molecule inhibitor of ASH1L, demonstrates similar anti‐fibrosis and tumor‐suppressive effects." (PMID 39377228, 2024). "Our results also verified that ASH1L at least partially inhibits T cell‐mediated anti‐tumor response by recruiting and polarizing M2‐like TAMs." (PMID 39377228, 2024). "In particular, H3K4me3 signal reduction in tumor cells was further exacerbated when ASH1L was knocked down in the cocultured HSCs and vice versa." (PMID 39377228, 2024). "Collectively, ASH1L is an H3K4me3 methyltransferase that consistently shows increased expression in activated HSCs and tumor cells both in vitro and in vivo." (PMID 39377228, 2024). "Labeling CD8+ T cells with carboxyfluorescein succinimidyl ester (CFSE) fluorescent dye, we found that double knockdown of ASH1L in tumor cells and HSCs induced polarized macrophages that promoted CD8+ T cell proliferation." (PMID 39377228, 2024). "The dysregulation of ASH1L is known to promote the progression of various aggressive solid cancers and is required for the activation of tumor-related gene expression and cellular growth." (PMID 36033518, 2022). "Additionally, MORF4L1 interacts with proteins such as ASH1L, activating histone methyltransferase activity and potentially altering tumor chromatin structure." (PMID 39757177, 2025). "Knocking down ASH1L in either HSCs or tumor cells could inhibit macrophage recruitment and reduce M2 macrophage marker genes expression, with the strongest effect seen in the double knockdown group." (PMID 39377228, 2024). "Foci formation assay demonstrated that double knockdown of ASH1L in tumor cells and HSCs induced polarized macrophages with the highest ability to inhibit tumor growth, as compared to polarized macrophages induced by single knockdown of ASH1L in either HCC or HSC." (PMID 39377228, 2024). "This suggests that ASH1L may function by modulating the tumor microenvironment." (PMID 39377228, 2024). "In addition, we identified mutations in epigenetic regulation genes, such as KMT2D, KMT2E, SMYD3, ASH1L, KMT2C, and KMD4B, in the tumor clones." (PMID 38010945, 2024). "The CCK‐8 assay revealed that the knockdown of ASH1L in tumor cells did not significantly affect cell proliferation." (PMID 39377228, 2024). "For example, TFs, such as ASH1L, CFLAR, HMGB3, ZNF160 and MATR3, displayed opposite behaviors on some cytokines; inflammatory factors; nuclear and tumor factors, such as IL-2, IL-6, NF-κB, and Irf3; immunogenic nucleic acids; papillomavirus E7/E6; caspase-3/caspase-8; Toll-like receptor; and so on." (PMID 28719625, 2017). "Besides, HIF-1α inhibition showed anti-tumor effects in the control group but not in the ASH1L depletion group." (PMID 40394007, 2025). "Interestingly, there was no significant changes between tumor and normal tissue in enzymes writing or erasing H3K4 marks including Kmt2a, Ash1l, Cxxc1, Kdm1a and Ezh2." (PMID 25823816, 2015).
neurodevelopmental disorder (7 papers, 2020 to 2025). A behavioral and cognitive disorder with onset during the developmental period that involves impaired or aberrant development of intellectual, motor, or social functions. "In conclusion, the identification of the novel ASH1L p.Lys827* nonsense variant contributes significant insights to the complex genetic landscape of ID and ASH1L-related neurodevelopmental disorders." (PMID 39902220, 2025). "The present study advances our understanding of ASH1L’s involvement in neurodevelopmental disorders by identifying a novel heterozygous nonsense variant, NM_018489.2: c.2479A > T (p.Lys827*), in a patient with mild ID." (PMID 39902220, 2025). "This variant adds to the growing body of evidence supporting ASH1L’s role in neurodevelopmental disorders and expands the known phenotypic spectrum of this condition." (PMID 39902220, 2025). "Variants in the NUP214 gene cause acute febrile encephalopathy and rare mutations in ASH1L are connected to numerous neurodevelopmental disorders [reviewed in]." (PMID 36061196, 2022). "Of note, haploinsufficiency of ASH1L has been shown to be associated with neurodevelopmental disorders." (PMID 32518592, 2020). "Individuals with ASH1L variants present with a broad spectrum of neurodevelopmental disorders." (PMID 38674358, 2024). "Mouse models with ASH1L exon 4 deletion resulting in a premature stop codon (p.V1693Afs*2) exhibit abnormal cortical neuron differentiation and craniofacial abnormalities, providing insights into the molecular mechanisms underlying ASH1L-associated neurodevelopmental disorders." (PMID 39902220, 2025). "This makes our discovery of a nonsense variant in a mildly affected individual particularly relevant for expanding the clinical profile of ASH1L-related neurodevelopmental disorders." (PMID 39902220, 2025). "In addition, ASH1L mutation have also been linked to seizures, which broadens the diversity of both genetic and clinical features seen in ASH1L-related neurodevelopmental disorders." (PMID 39902220, 2025). "Among the additional variants related to neurodevelopmental disorders identified by Trio-WES, ALDH18A1 (NM_002860.4): c.683C>T (p.P228L) and ASH1L (NM_018489.3): c.6238G>A (p.V2080I) were de novo and paternally inherited, respectively, but did not fulfill the criteria for co-segregation." (PMID 40574801, 2025).
neurological diseases (2 papers, 2017 to 2023). "The association of ASH1L deficits with multiple neurological disorders suggests that common downstream mechanisms could underlie the diverse neuropathology in ASH1L-related disorders." (PMID 36845425, 2023).
brain disorder (1 paper, 2021). A disease affecting the brain or part of the brain. "ASH1L is recognized as a top-ranking risk factor for multiple brain diseases, including ASD2, Epilepsy4,5, and ID22." (PMID 34782621, 2021). "Over 100 loss-of-function (LOF) mutations in the coding regions of ASH1L have been discovered, and individuals harboring ASH1L mutations display a variety of symptoms associated with these brain disorders, including social deficits, repetitive behaviors, and seizures." (PMID 34782621, 2021). "To investigate the biological function of ASH1L and its mechanistic link to brain disorders, we generated an Ash1L short hairpin RNA (shRNA) viral vector (GFP-tagged)." (PMID 34782621, 2021).
infectious disease (1 paper, 2022). A disorder directly resulting from the presence and activity of a microbial, viral, or parasitic agent in humans. "We reveal that the circTmem241-Nono-Ash1l-Elk3 axis is required for the ILCP differentiation into ILC3P and ILC3 maturation, which is important to manipulate this axis for ILC development on treatment of infectious diseases." (PMID 35953472, 2022).
ASH1L also shares sentences with these, for which no sentence is quoted: Tourette syndrome (2 papers); bacterial infection (1); cervical carcinoma (1); Cockayne Syndrome B (1); COVID-19 (1); fibrosis (1); gastroesophageal reflux disease (1); heart failure (1); liver fibrosis (1); myeloid leukemia (1); non-small cell lung carcinoma (1); oesophageal cancer (1); osteosarcoma (1); pancreatic carcinoma (1); Pilarowski-Bjornsson Syndrome (1); renal carcinoma (1); Splenomegaly (1); Sturge-Weber syndrome (1); thyroid follicular carcinoma (1).